HFE (homeostatic iron regulator)
Description:
Binds to transferrin receptor (TFR) and reduces its affinity for iron-loaded transferrin.
Synonyms: HLA-H; HFE1; HH; MVCD7; TFQTL2
Tractability: Antibody: UniProt places it where antibodies can reach, with high confidence; its Gene Ontology location is reachable by antibodies, with high confidence; UniProt predicts a signal peptide or a membrane-spanning region; the Human Protein Atlas places it where antibodies can reach. PROTAC: ubiquitination databases record sites on it.
Gene: Protein-coding gene on chromosome 6 (26,087,226 to 26,098,343, forward strand). Ensembl gene ENSG00000010704.
Subcellular location: Cell membrane
Subcellular location (Human Protein Atlas): Plasma membrane; Nucleoplasm
Pathways (Reactome):
Transport of small molecules: Transferrin endocytosis and recycling
Gene Ontology:
Molecular function: beta-2-microglobulin binding; co-receptor binding; peptide antigen binding; protein binding; signaling receptor binding; transferrin receptor binding; transporter activator activity
Biological process: BMP signaling pathway; cell surface receptor signaling pathway; cellular response to iron ion; intracellular iron ion homeostasis; multicellular organismal-level iron ion homeostasis; negative regulation of antigen processing and presentation of endogenous peptide antigen via MHC class I; negative regulation of CD8-positive, alpha-beta T cell activation; negative regulation of proteasomal ubiquitin-dependent protein catabolic process; negative regulation of T cell cytokine production; negative regulation of ubiquitin-dependent protein catabolic process; positive regulation of peptide hormone secretion; positive regulation of receptor-mediated endocytosis; positive regulation of SMAD protein signal transduction; receptor-mediated endocytosis; regulation of iron ion transport; regulation of protein localization to cell surface; response to iron ion; transferrin transport; antigen processing and presentation; antigen processing and presentation of peptide antigen via MHC class I; positive regulation of gene expression; protein-containing complex assembly; response to iron ion starvation; regulation of T cell mediated immunity
Cellular component: apical part of cell; basal part of cell; cytoplasmic vesicle; early endosome; external side of plasma membrane; extracellular region; HFE-transferrin receptor complex; MHC class I protein complex; perinuclear region of cytoplasm; plasma membrane; recycling endosome
Genetic constraint (gnomAD): Loss-of-function variants: 34 observed, 43.66 expected, observed/expected ratio (o/e) 0.78, 90% interval 0.59 to 1.04. The upper end of that interval is the gene's LOEUF score, 1.04, which puts it in group 4 of 6, group 1 being the genes least tolerant of losing a copy. Missense variants: 376 observed, 456.2 expected, observed/expected ratio (o/e) 0.82, 90% interval 0.76 to 0.9. Synonymous variants: 157 observed, 175.82 expected, observed/expected ratio (o/e) 0.89, 90% interval 0.78 to 1.02.
Gene-disease validity (ClinGen):
ClinGen rates the evidence that HFE causes each of these diseases.
hemochromatosis type 1 (autosomal recessive): Definitive. Hemochromatosis type 1 (classic) is the most common form of hereditary hemochromatosis (HH), a group of diseases characterized by excessive tissue iron deposition.
Homologues: Orthologues: chimpanzee HFE (99% identical), macaque HFE (94% identical), pig HFE (78% identical), guinea pig HFE (73% identical), rabbit HFE (72% identical), rat Hfe (70% identical), mouse Hfe (68% identical). Paralogues in human: HLA-A (36% identical), HLA-B (36% identical), HLA-C (36% identical), HLA-F (35% identical), HLA-G (35% identical), HLA-E (34% identical), MR1 (33% identical), MICB (29% identical), AZGP1 (28% identical), MICA (27% identical), FCGRT (27% identical), CD1A (20% identical), and 10 more.
Diseases named in the same sentence as HFE in open-access papers:
HFE is named in the same sentence as 169 diseases in open-access papers, as found by Europe PMC text mining. Sharing a sentence is not in itself a finding about the gene and the disease. The quoted sentences say what the papers report.
hemochromatosis (143 papers, 2004 to 2026). A disorder of iron metabolism characterized by a triad of HEMOSIDEROSIS; LIVER CIRRHOSIS; and DIABETES MELLITUS. "The most common genetic disease of iron deposition is classic hemochromatosis (HH) type 1, which is caused by mutations of HFE." (PMID 40149659, 2025). "HFE is an important protein implicated in hepcidin biosynthesis and HFE mutations have been associated with the majority of hereditary hemochromatosis cases." (PMID 40149659, 2025). "The lead variant at the HFE locus is a known cause of hemochromatosis, a disorder that has been associated with both HCC and biliary tract cancer." (PMID 40823170, 2025). "Mostly, hemochromatosis (HH) is attributed to genetic mutations, with C282Y and H63D mutations of the HFE gene being the primary etiological factors in hereditary hemochromatosis." (PMID 39798849, 2025). "Mutations in the HFE gene are the most common cause of hemochromatosis in adults, primarily characterized by iron overload in various organs and tissues, which results in insufficient hepcidin expression." (PMID 39941155, 2025). "The most common genetic mutation in patients with HH, also known as type 1 hemochromatosis, is in the HFE gene." (PMID 41341325, 2025). "Hemochromatosis involves mutations in the HFE protein, leading to iron overload, while atrial fibrillation (AF) is characterized by triggers and substrates that initiate and maintain the arrhythmia." (PMID 38333328, 2024). "Hemostatic iron regulator (HFE)-hemochromatosis is a common disorder of iron metabolism caused by a homozygous mutation (p.C282Y) of the HFE gene, which can result in significant clinical manifestations and iron overload in up to 40% of men and 12% of women." (PMID 39131712, 2024). "The most common form of hereditary hemochromatosis is linked to mutations in the HFE gene, particularly the C282Y mutation." (PMID 39323676, 2024). "Mutations in the gene HFE are also implicated in Hemochromatosis which occurs when body builds up excessive amounts of iron leading to potential damage and dysfunction in vital organs such as the liver, heart and pancreas." (PMID 38865495, 2024). "The diagnostic process for hemochromatosis involves assessing iron markers through blood tests, genotypic testing for specific HFE gene mutations, and considering the need for a liver biopsy in certain cases." (PMID 38333328, 2024). "It elucidates diverse inheritance patterns and clinical manifestations by exploring mutations in critical genes such as HFE (hemochromatosis), HJV (hemojuvelin), HAMP (hepcidin antimicrobial peptide), TfR2 (transferrin receptor 2), and FP (ferroportin)." (PMID 39114232, 2024). "Hemochromatosis, the most common cause being primary hemochromatosis, is an autosomal recessive condition where homozygotes with a mutation in the HFE protein experience increased iron absorption despite a normal dietary intake." (PMID 38333328, 2024). "• Hemochromatosis involves mutations in the HFE protein, leading to iron overload.• AF is characterized by triggers and substrates that initiate and sustain the arrhythmia." (PMID 38333328, 2024). "Significantly, the variant rs1800562 in the HFE gene, commonly referred to as C282Y, is associated with a severe manifestation of Hemochromatosis." (PMID 39170693, 2024). "Mutations in five key genes - HFE (hemochromatosis), HJV (hemojuvelin), HAMP (hepcidin antimicrobial peptide), TfR2 (transferrin receptor 2), and FP (ferroportin) - are responsible for HH." (PMID 39114232, 2024). "There are two main mutations in the homeostatic iron regulator (HFE) gene implicated in developing hemochromatosis, namely, the cysteine-to-tyrosine substitution at amino acid 282 (C282Y) and histidine-to-aspartic acid substitution at 63 (H63D)." (PMID 39867034, 2024).
hemochromatosis (continued). "In patients with hemochromatosis, the molecular finetuning of physiological intestinal iron uptake is set off primarily due to genetic mutations in the HFE gene that cause an increased absorption of iron despite a normal dietary iron intake." (PMID 38473913, 2024). "Variants in the HFE gene were found in 8 out of 40 patients (20 %), but in only one patient the results were associated with an increased risk for hemochromatosis." (PMID 39309680, 2024). "Hemochromatosis involves mutations in the HFE protein, leading to iron overload, while AF is characterized by triggers and substrates that initiate and maintain the arrhythmia." (PMID 38333328, 2024). "As a result, mutations in the HFE gene lead to excess iron absorption and iron overload in hemochromatosis." (PMID 38473913, 2024). "Hemochromatosis occurs in homozygotes with a mutation of the HFE gene at a prevalence of 1:300 to 1:500 individuals." (PMID 38473913, 2024). "Hemochromatosis occurs in homozygotes with a mutation of the hemochromatosis gene (HFE) protein with a prevalence of 1:300 to 1:500 individuals." (PMID 38928368, 2024). "Hemochromatosis, a prevalent inherited metabolic disorder in white populations, often results from a C282Y mutation in the HFE gene, where a G > A mutation at c.845 disrupts HFE protein folding, preventing it from reaching the cell membrane." (PMID 39726634, 2024). "Type 1 hemochromatosis, also known as classic hereditary hemochromatosis, is caused by mutations in the HFE gene, most commonly C282Y and H63D." (PMID 39323676, 2024). "Hemochromatosis in whites of Western European descent is usually due to homozygosity for a common missense allele p.C282Y (rs1800562) of the homeostatic iron regulator (HFE, chromosome 6p22.2)." (PMID 38186421, 2023). "Type 1 hereditary hemochromatosis is caused by being a homozygous carrier of missense mutations (His-63-Asp or Cys-282-Tyr) in the homeostatic iron regulator (HFE) gene; these mutations lead to increased Fe uptake from the gastrointestinal tract." (PMID 36357556, 2022). "In 1996, Feder and colleagues discovered the HFE gene (homeostatic iron regulator, chromosome 6p22.2) and two common HFE missense alleles in patients with hemochromatosis." (PMID 35659379, 2022). "Hemochromatosis is one of the most common inherited metabolic diseases among white populations and predominantly originates from a homozygous C282Y mutation in the HFE gene." (PMID 36064805, 2022). "Several hepcidin regulators control its synthesis, and most of those are included in the mutated genes, which lead to hemochromatosis (e.g., HFE, TfR2, HEF2, HAMP etc.)." (PMID 35453939, 2022). "The hereditary hemochromatosis-associated membrane proteins HFE, TFR2, and HJV are required for adequate hepatic expression of the iron hormone hepcidin." (PMID 35163229, 2022). "Heterozygote carriers of homeostatic iron regulator (HFE): p.(Cys282Tyr) in hemochromatosis are reported to have some protection from iron deficiency." (PMID 35336849, 2022). "Additional evidence on the association between iron and cancer is provided by the studies of subjects affected by hemochromatosis, caused by mutations in the HFE gene, connoted by the progressive accumulation of iron because of altered iron transport proteins." (PMID 35745285, 2022). "Human leukocyte antigen (HLA)-A*03, hemochromatosis ancestral haplotype marker, was associated with greater iron overload in hemochromatosis cohorts reported before discovery of the HFE gene." (PMID 35659379, 2022). "TSC is often elevated in patients with HFE-linked hemochromatosis, while the H63D HFE gene polymorphism is considered as a risk factor for ALS." (PMID 33419478, 2021). "HFE hemochromatosis is characterized by increased iron absorption and iron overload due to variants of the iron-regulating HFE gene." (PMID 34440336, 2021).
hemochromatosis (continued). "Most hemochromatosis genetic base conditions are linked to BMP2 as a result of homozygosity for the C282Y missense mutations that cause modification in the HFE gene." (PMID 34780475, 2021). "The HFE gene rs1800562(A > G) variant was associated with hemochromatosis previously, which leads to excessive iron accumulation in the liver and hepatocyte injury." (PMID 33925809, 2021). "A functional link between the hereditary hemochromatosis (HH) susceptibility gene HFE (also known as homeostatic iron regulator), iron status and adaptive T cell function has been suggested." (PMID 33926483, 2021). "Variants in the gene HFE (homeostatic iron regulator), which cause hemochromatosis, accounted for 87% of variants in this category." (PMID 34495297, 2021). "In European ancestry populations, the HFE p.C282Y variant can cause iron overload and hemochromatosis, mostly in homozygous males." (PMID 33427739, 2021). "Retinal abnormalities have been reported in a 49-year-old hemochromatosis patient with homozygosity for the C282Y polymorphism in the HFE gene." (PMID 35185447, 2021). "Case 4 (19ZC160) has five missense variants, including His63Asp, within the HFE gene, involved in iron absorption and associated with hemochromatosis (OMIM#235200) and microvascular complications of diabetes 7 (OMIM#612635)." (PMID 33815474, 2021). "The most common form of hereditary hemochromatosis in Western Europe is due to a homozygous mutation (p.(Cys282Tyr) or C282Y), in the HFE gene which encodes hereditary haemochromatosis protein." (PMID 33457423, 2020). "An exception here is HFE rs1800562 (Cys282Tyr), a well-known variant associated with hemochromatosis." (PMID 31797629, 2020). "The most common form of hemochromatosis is associated with mutations in the HFE, an atypical major histocompatibility class I molecule." (PMID 31442254, 2019). "Most hereditary hemochromatosis is due to a mutation of the HFE gene, which can regulate iron uptake by interfering with the interactions between transferrin and transferrin receptor." (PMID 31083351, 2019). "Homozygosity for the p.C282Y substitution in the HFE protein encoded by the hemochromatosis gene on chromosome 6p (HFE) is a common genetic trait that increases susceptibility to iron overload." (PMID 30913256, 2019). "In this case the simulation of hemochromatosis is achieved by silencing hepcidin synthesis at the transcription level (HAMP-/-) instead of the HFE-/- mutation." (PMID 30608934, 2019). "A very low prevalence of the HFE gene mutation would explain the low prevalence of hemochromatosis in the Han population." (PMID 30691187, 2019). "It is noteworthy that association between hemochromatosis-related functional variant in the HFE gene and primary VVs was revealed in our previous candidate-gene study in ethnic Russian individuals." (PMID 30998689, 2019). "Of these, mutations in the HFE gene located on chromosome 6 are by far the most common and >80 % of patients with hemochromatosis are homozygous for HFE mutation C282Y (rs1800562, G845A)." (PMID 27363994, 2016). "In humans, ISD or hemochromatosis is often associated with an autosomal recessive disorder caused by a mutation on the hemochromatosis (HFE) gene, which leads to increased iron absorption." (PMID 27232336, 2016). "Hemochromatosis due to mutations in the hemochromatosis Fe (HFE) gene is the most common, autosomal recessive, form of inherited iron-overload disorder among people originating from northwestern Europe." (PMID 26380265, 2015). "The presence of mutations in the HFE gene (major in C282Y variant and less common in H63D variant) leads to hemochromatosis." (PMID 24988074, 2014). "A potential candidate gene for susceptibility to lead exposure is the hemochromatosis (HFE) gene encoding the HFE protein." (PMID 24988074, 2014).
hemochromatosis (continued). "The two variants in the HFE gene are responsible for most cases of hereditary hemochromatosis, and they are associated with iron overload when present in the homozygous (C282Y/C282Y) or compound heterozygous (C282Y/H63D) state." (PMID 23750121, 2013). "Previous studies found effect modification of associations between traffic-related air pollution and cardiovascular outcomes by polymorphisms in the hemochromatosis gene (HFE)." (PMID 23413885, 2013). "Two common missense polymorphisms of this gene, HFE C282Y and H63D are associated with the disease state of hemochromatosis, an autosomal recessive genetic disease that causes an increase in absorption of ingested iron." (PMID 23413885, 2013). "Recent data confirm the involvement of genes that encode proteins HFE (hemochromatosis), HJV (haemojuvelin), TfR2 (transferrin receptor), SLC40A1 (ferroportin) in maintaining iron homeostasis by stimulating the production of hepcidin." (PMID 24146699, 2013). "Association of the HFE (hemochromatosis) gene with prostate cancer highlight the crosstalk between pathology of hemochromatosis and prostate cancer." (PMID 22662242, 2012). "Genetic hemochromatosis was investigated only for the HFE gene, with the finding of heterozygosis of the mutation H36D; the mother was negative for HFE mutations and the father had H63D/C282Y heterozygosis." (PMID 21569394, 2011). "We evaluated associations of manganese with functional variants in three candidate iron metabolism genes: HFE [hemochromatosis], TF [transferrin], and ALAD [δ-aminolevulinic acid dehydratase]." (PMID 22074419, 2011). "The hemochromatosis gene encodes HFE, a transmembrane glycoprotein which normally associates with transferrin receptor 1 (TfR1) and decreases intracellular iron and ferritin concentrations." (PMID 20670400, 2010). "A nonsynonymous SNP (rs1800562, C→Y) within the hemochromatosis gene (HFE) on chromosome 6p22.1 was associated with MCH (P = 2.8×10−9, R2 = 1.1%)." (PMID 20927387, 2010). "Despite the high prevalence of mutations in the HFE gene, the phenotypic expression of hemochromatosis varies considerably and both environmental and genetic factors appear to make important contributions to this variation." (PMID 18366708, 2008). "About 90% of clinical cases of iron overload (hemochromatosis) in populations of northern European origin are homozygous for the 845 G → A mutation in the HFE gene responsible for the C282Y substitution in the HFE protein." (PMID 18366708, 2008). "In Northern Europe, most patients with HH are homozygous for a single mutation (C282Y) in the HFE gene (which encodes the hereditary hemochromatosis [HFE] protein)." (PMID 17945001, 2007). "Hemochromatosis associated with homozygosity for HFE C282Y on Ch6p occurs predominantly in whites of western European descent, although the iron-related phenotypes of persons with this type of hemochromatosis are variable." (PMID 16533407, 2006). "Most European studies have reported that 60-90% of typical hemochromatosis patients are homozygous for the C282Y mutation of the HFE gene (C282Y/C282Y)." (PMID 16878186, 2006). "The C282Y mutation in the HFE gene causing hemochromatosis, and the gene coding for δ-aminolevulinic acid dehydratase, an enzyme of heme synthesis, are both associated with increased lead absorption." (PMID 16002380, 2005). "Mutated HFE protein is known to cause hemochromatosis, in which large quantities of iron are deposited in internal organs." (PMID 15198918, 2004). "Hemochromatosis in white people of European descent is usually associated with homozygosity for p.C282Y (rs1800562), a missense allele of the homeostatic iron regulator (HFE, chromosome 6p22.2)." (PMID 39866924, 2025). "Thus, mutations in the HFE gene lead to excess iron absorption and iron overload in hemochromatosis." (PMID 38928368, 2024).